MIF (macrophage migration inhibitory factor)
Diseases named in the same sentence as MIF in open-access papers (continued):
Sharing a sentence is not in itself a finding about the gene and the disease.
Impaired glucose tolerance (13 papers, 2011 to 2024). An abnormal resistance to glucose, i.e., a reduction in the ability to maintain glucose levels in the blood stream within normal limits following oral or intravenous administration of glucose. "MIF gene interference is linked to impaired glucose tolerance, and lower blood glucose level in diabetic apoE−/− mice." (PMID 25661015, 2015). "Circulating plasma MIF and mononuclear cell MIF mRNA expression are associated with increasing BMI and fatty acid concentration, impaired glucose tolerance and T2D, whereas reducing body weight or metformin treatment decreases serum MIF levels." (PMID 25412423, 2014). "Interestingly, in our present study, we did not conclude any correlation between MIF and plasma glucose or HbA1c levels, despite a previous study suggesting a stepwise increase in serum MIF associated with the progression from impaired glucose tolerance (IGT) to type 2 diabetes (T2D)." (PMID 38802393, 2024). "Macrophage migration inhibitory factor (MIF), associated with impaired glucose tolerance, is increased in diabetic patients with LV diastolic dysfunction." (PMID 35204091, 2022). "As already mentioned, increased serum MIF concentration in impaired glucose tolerance and T2D was reported." (PMID 30302090, 2018). "Plasma MIF concentrations and PBMC MIF mRNA are positively associated with BMI, FFA concentration, impaired glucose tolerance (IGT), and IR." (PMID 23675368, 2013). "Positive association plasma MIF with impaired glucose tolerance and T2D independent of plasma CRP and IL-6." (PMID 26124760, 2015). "Plasma MIF levels higher in impaired glucose tolerance rats than in controls." (PMID 26124760, 2015). "Among the proinflammatory cytokines, several clinical studies established that macrophage migration inhibitory factor (MIF) levels positively correlated to body mass index, plasma free fatty acids and impaired glucose tolerance." (PMID 23536817, 2013). "To confirm the clinical observation, we also studied MIF expression in prediabetic rats with impaired glucose tolerance (IGT) and relationship between MIF and GRK2 expression in H9C2 cardiomyoblasts exposed to high glucose." (PMID 21283592, 2011).
kidney (13 papers, 2009 to 2026). "ISO-1 is one of the most used and studied small molecules targeting MIF and was found to have anti-inflammatory properties attenuating acute kidney and lung injury in many models." (PMID 35091838, 2022). "Compared to wild-type mice, deletion of MIF significantly aggravated acute kidney injury as shown by higher serum creatinine levels." (PMID 35091838, 2022). "In cell culture and animal models of genitourinary cancer, inhibiting MIF activity can reduce the malignant biological behaviors of cancer, such as cell proliferation, angiogenesis, and tumor aggressiveness." (PMID 35036405, 2021). "The tumor-promoting properties of MIF have been widely reviewed elsewhere, but the results previously presented demonstrate that at some point in colorectal carcinogenesis, MIF is beneficial for the host." (PMID 31360118, 2019). "Macrophage migration inhibitory factor (MIF) is a pro-inflammatory cytokine expressed by urothelial cells that mediates bladder inflammation." (PMID 21209875, 2010). "The reason for these dual effects of MIF in acute kidney injury remains unknown." (PMID 35091838, 2022). "Renal vasculitis correlated with kidney PD-1, CCL1, MIF, Granzyme A, IL-15, and BAFF." (PMID 42182101, 2026). "In addition, we also found a reduction in apoptosis in plMDCK cysts upon application of ISO-1 which is in line with a recent report that showed that mice lacking MIF had less apoptosis in acute kidney injury upon application of cisplatin." (PMID 32885302, 2020).
breast tumor (12 papers, 2009 to 2026). "The observation that abundant MIF expression is significantly associated with breast tumours of small size supports the notion that intracellular MIF can inhibit tumour cell proliferation." (PMID 19602265, 2009). "Thus surprisingly, abundant MIF expression in breast tumour tissue correlates with markers associated with a favourable prognosis, i.e. pT, positive ER and PR status." (PMID 19602265, 2009). "Given the emerging interplay between WISP1 and MIF and their critical roles in shaping the TME to exacerbate tumor aggressiveness, this study aims to elucidate how this WISP1/MIF axis influences breast tumor plasticity and aggressiveness." (PMID 41597235, 2026). "The present study demonstrates that MARCO is expressed on MDSCs, and breast tumor-derived exosomes (TDEs) enriched with macrophage migration inhibitory factor (MIF) promote MDSC differentiation and amplify immunosuppressive activity by up-regulating MARCO." (PMID 40695812, 2025). "MIF is upregulated in human breast tumors and high levels of MIF are correlated with patients’ overall poor survival." (PMID 34012010, 2021). "MIF is significantly upregulated in breast tumors and correlates with poor overall survival in patients." (PMID 34012010, 2021). "MIF mRNA levels were significantly increased in primary and metastatic breast tumors as compared with normal breast tissues." (PMID 34012010, 2021). "Conversely, in the tumor microenvironment (TME), tumor-derived HSP90 chaperone complex can stabilize macrophage migration inhibitory factor (MIF) and thereby promote breast tumor progression." (PMID 33023034, 2020). "Although MIF has been shown before to enhance breast tumor growth, its role in TNBC is yet unexplored." (PMID 32943608, 2020). "Immunohistochemistry was used to evaluate VEGFA and MIF levels in breast tumors and normal breast tissues; qPCRs and western blots were used to validate the expression of clinical immuno-oncology (IO) therapeutic targets CD274 (PD-L1) and IL8 in cell lines." (PMID 31293831, 2019). "Interfering with MIF effects in breast tumors in a therapeutic perspective remains an attractive but complex challenge, notably depending on the development of suitable MIF inhibitors." (PMID 24939415, 2014). "Interfering with MIF effects in breast tumors in a therapeutic perspective remains an attractive but complex challenge." (PMID 24939415, 2014). "In fact, the assumption that MIF promotes breast tumour cell invasiveness was underscored by Matrigel invasion assays using MDA-MB-231." (PMID 19602265, 2009). "In addition to the immunohistochemical analysis of MIF expression in breast tumors, we used an ELISA to compare MIF levels in serum of 36 patients with BC to those of 22 healthy individuals." (PMID 24939415, 2014). "Indeed, the HSP90 inhibitor 17-N-allylamino-17-demethoxygeldanamycin (17-AAG) inhibits growth of MIF-expressing breast tumors in mice." (PMID 24939415, 2014). "MIF protein expression was observed in normal breast epithelial cells and breast tumour cells." (PMID 19602265, 2009). "During breast tumor progression, HSP90 was activated and protected migration inhibitory factor (MIF) from degradation, inhibition of HSP90 destabilized MIF and repressed the tumor growth." (PMID 34956178, 2021).
head and neck squamous cell carcinoma (12 papers, 2014 to 2026). A squamous cell carcinoma that arises from any of the following anatomic sites: lip and oral cavity, nasal cavity, paranasal sinuses, pharynx, larynx, and salivary glands. "Increased MIF expression has been observed in head and neck squamous cell carcinomas (HNSCC), specifically in the nasopharygeal carcinoma (NPC), hypopharynx carcinoma, laryngopharyngeal carcinoma, and oral squamous cell carcinoma (OSCC)." (PMID 41159021, 2025). "For example, a study developed a prognostic model based on four cellular senescence-related genes (BAK1, DKK1, CDKN2A, and MIF) to predict the survival rate of individuals with head and neck squamous cell carcinoma." (PMID 37580647, 2023). "MIF has been reported to be overexpressed in multiple cancers, including gastric adenocarcinoma, head and neck squamous cell carcinoma, esophageal squamous cell carcinoma, colorectal, pancreatic, ovarian, and prostate cancers." (PMID 26530123, 2015). "A study of patients with head and neck squamous cell carcinoma revealed correlations between low and high tumoral immunohistochemical expression of MIF and poor survival, and between moderate expression and improved survival." (PMID 25289107, 2014). "Head and neck squamous cell carcinoma (HNSCC) cell-derived MIF induces the chemotaxis and activation of neutrophils through a p38-dependent mechanism." (PMID 29556041, 2018). "In head and neck squamous cell carcinoma (HNSCC), tumor cells secrete MIF to activate the JAK/STAT3 pathway in myeloid cells, which in turn induces the formation of apCAFs." (PMID 41164803, 2025). "Recent study demonstrated that MIF promoted tumorigenesis and tumor progression and played a critical role in various kinds of human cancer including head and neck squamous cell carcinoma(HNSCC)." (PMID 27788497, 2017).
tuberculosis (12 papers, 2010 to 2024). A chronic, recurrent infection caused by the bacterium Mycobacterium tuberculosis. "We conducted a search of case-control studies on the associations of -173 G > C variant of MIF with susceptibility to tuberculosis in PubMed, ISI Web of Science, and Scopus." (PMID 28507475, 2017). "Five studies involving 929 cases and 876 controls were pooled together for assessment of the overall association between MIF -173 G > C variant and the risk of tuberculosis." (PMID 28507475, 2017). "The present study aimed to perform a meta-analysis of all eligible studies to evaluate the overall association between the MIF -173 G > C polymorphism and risk of tuberculosis." (PMID 28507475, 2017). "A similar role of MIF was also observed in Tuberculosis, in which high-expression MIF allele confer disease protection whereas circulating MIF that were found to be elevated in patients with active pulmonary tuberculosis, seem to contribute to disease progression." (PMID 34662363, 2021). "Additionally, in patients with tuberculosis, low levels of anti-MIF autoantibodies are believed to be associated with increased activation of MIF." (PMID 33238656, 2020). "The aim of the present meta-analysis was to find out the impact of MIF -173 G > C polymorphism on risk of tuberculosis (TB)." (PMID 28507475, 2017). "MIF -173 G > C gene polymorphism may affect immunity in an individual and leads to susceptibility to tuberculosis (TB)." (PMID 29208960, 2017). "This study was designed to explore the significance of MIF serum levels in predicting the prognosis of pulmonary tuberculosis (PTB) following anti-TB treatment." (PMID 30841876, 2019). "Here, we focus on the main signaling pathways involved in the fibroblast formation in the core area of tuberculosis, such as THBS, CD99, MIF, COMPLENENT, CXCL, THY1, and GAS pathways." (PMID 39431015, 2024). "Therefore, we hypothesized that, in response to increased MIF levels in tuberculosis, antibodies against MIF would be lower in TB patients than in healthy individuals." (PMID 33238656, 2020). "Moreover, MIF levels were not quantified; a correlation study between different genotypes and MIF levels in patients and controls might help to explain the association between MIF -173 G>C gene polymorphism and susceptibility/resistance to tuberculosis." (PMID 32525926, 2020). "We measured immunoglobulin (Ig)A and IgG responses to MIF in individuals with either active tuberculosis (ATB; n = 65), latent tuberculosis (LTBI; n = 53), or in non-infected individuals (NI; n = 62)." (PMID 33238656, 2020).
brain tumors (11 papers, 2012 to 2023). "The association of MIF with the progression of malignant brain tumors places this cytokine in center stage." (PMID 22973314, 2012). "It has been shown that brain tumors escape pro-inflammatory M1 conversion of microglia via CD74 activation through the secretion of MIF which results in a M2 shift of microglial cells." (PMID 29707160, 2018). "Acting as an endogenous glucocorticoid antagonist, MIF thus represents a relevant resistance gene in brain tumor therapies." (PMID 22973314, 2012). "We consider the possibility of MIF targeting in neurodegenerative processes and brain tumors by novel MIF-neutralizing approaches." (PMID 22973314, 2012). "Since the Warburg effect is one characteristic feature of malignant gliomas (i.e., primary brain tumors derived from glial and precursor cells), further investigation into the metabolic effects of MIF in brain tumor cells would be highly desirable." (PMID 22973314, 2012). "It is suggested that brain tumors secrete MIF to control the activity of accumulating tumor-promoting cells, which in turn might have inductive tumor-progressive as well as proangiogenic effects." (PMID 22973314, 2012). "Whether MIF upregulates phosphofructo-2-kinase and glycolysis in brain tumor cells with subsequently increased lactate release has not yet been tested." (PMID 22973314, 2012).
cardiomyopathy (11 papers, 2011 to 2025). A disease of the heart muscle or myocardium proper. "In a model of doxorubicin-induced cardiomyopathy, MIF deficiency exacerbated cardiomyopathy and mortality, suggesting its cardioprotective role." (PMID 40092999, 2025). "As MIF may contribute to the pathogenesis of MetS-associated cardiomyopathy and modify cardiac metabolism, we tested the effects of MIF inhibition in mice fed with a fat-enriched diet." (PMID 23536817, 2013). "In cardiomyopathy patients, myocardial MIF expression was elevated in patients with ischemic cardiomyopathy compared with non-ischemic cardiomyopathy." (PMID 40092999, 2025). "Among studied cytokines, some were associated with general susceptibility to T. cruzi infection (IFN-γ, MIF, IL-4, TNF, TGF-β, and IL-18) and others with cardiomyopathy development (TNF, IL-1, BAT1, MCP-1, LT-α, IL-12, and IL-10)." (PMID 29670670, 2018). "We here report on MIF expression in the failing human heart and assess myocardial MIF in different types of cardiomyopathy." (PMID 29027966, 2017). "The present study is the first to prove MIF mRNA expression in the failing human heart and the first to describe variable expression patterns depending on the etiology of cardiomyopathy." (PMID 29027966, 2017). "MIF and HIF-1α expression levels in myocardial samples showed a close correlation (R2 = 0.6971, p < 0.0001, n = 30) hinting at an association with hypoxia-induced HIF-1α expression with consecutive MIF gene regulation in cardiomyopathy." (PMID 29027966, 2017). "To verify the role of MIF and GDF-15 in iPSC-MSCs-CdM for the treatment of Dox-induced cardiomyopathy, we compared the cardioprotective effects of iPSC-MSCs-CdM with immunodepletion of MIF and GDF-15 in iPSC-MSCs-CdM in a mouse model of AIC." (PMID 26057572, 2015). "MIF and HIF-1α expression depends on the underlying type of cardiomyopathy." (PMID 29027966, 2017). "Moreover, other SNP related to other cytokines that could be related to susceptibility to T. cruzi infection (IFN-γ, MIF, IL-4, TNF, TGF-β, and IL-18) or cardiomyopathy development (TNF, IL-1, BAT1, MCP-1, LT-α, IL-12, and IL-10) were not studied." (PMID 29670670, 2018).
Cognitive impairment (11 papers, 2013 to 2026). Abnormal cognition is characterized by deficits in thinking, reasoning, or remembering. "The next study by this group showed the highest levels of MIF in the brain cytosol and CSF in a mild cognitive impairment group of patients (MCI) that has a high risk to develop AD over time, thus providing evidence that the neuroinflammation occurs early, at predementia stages of AD." (PMID 38178143, 2024). "Furthermore, we evaluated the long-term cognitive outcome of these patients and determined associations between the inter-individual variability of MIF concentrations after ex vivo stimulatory experiments and cognitive impairment." (PMID 33407905, 2021). "Although with this study we cannot prove a causal relationship, we hypothesize that prolonged MIF upregulation contributes to the cognitive impairments of survivors of pneumococcal meningitis." (PMID 33407905, 2021). "Subsequently, we investigated whether variability of MIF concentration after ex vivo stimulation was associated with cognitive impairment after pneumococcal meningitis in a long-term follow up study." (PMID 33407905, 2021). "Subsequently, we studied whether individual ex vivo MIF response years after meningitis was associated with the development of cognitive impairment." (PMID 33407905, 2021). "Furthermore, we found associations between high MIF levels and occurrence of cognitive impairment, suggesting MIF contributes to cognitive impairments in pneumococcal meningitis." (PMID 33407905, 2021). "AD and LongC had six common proteins elevated in people with cognitive impairment (MIF, ENO1, MESD, NUDT5, TNFSF14 and FYB1)." (PMID 38612641, 2024). "Previous studies show that MIF is elevated in a continuum in patients with mild cognitive impairment progressing to AD." (PMID 38612641, 2024). "Total Fazekas score and serum MIF level were found to be significant factors for diagnosing cognitive impairment due to CSVD." (PMID 37190581, 2023). "Delving into the possible role of CD74high microglia, one of the high-affinity ligands of CD74 is macrophage migration inhibitory factor (MIF), a pro-inflammatory cytokine that has been reported to contribute to cognitive impairment in individuals with AD dementia in several studies." (PMID 41282231, 2025). "Therefore, MIF can promote the occurrence and progression of CSVD through different pathogeneses, which in turn causes cognitive impairment." (PMID 37190581, 2023). "Elevated and detrimental MIF levels have direct detrimental effects on the brain, and contribute pathologically to the development of epileptic seizures, and to the additional brain damage and cognitive impairments that characterize NS." (PMID 34662363, 2021). "In the future, multicenter prospective cohort studies need to be carried out to explore in depth the role of MIF on the occurrence and development of CSVD and the mechanism of cognitive impairment related to CSVD." (PMID 37190581, 2023). "The authors also studied expression and function of MIF in the transgenic model of AD that can be observed in APP23/PS45 double transgenic mice that develop a significant amount of plaques and cognitive impairments." (PMID 31936865, 2020). "Interestingly, MIF, a high-affinity ligand of CD74, has been reported to contribute to cognitive impairment in individuals with AD dementia in several studies." (PMID 41282231, 2025). "Elevated MIF concentration was detected in the cerebrospinal fluid of AD patients but not in that of the patients suffering from mild cognitive impairment and vascular dementia." (PMID 31174614, 2019). "Finally, a study from a German group confirmed in 2009 that elevated CSF levels of MIF were observed both in patients with MCI and AD as compared to subjects without cognitive deficits." (PMID 31936865, 2020).